PILRA (paired immunoglobin like type 2 receptor alpha)
Description:
Paired receptors consist of highly related activating and inhibitory receptors and are widely involved in the regulation of the immune system. PILRA is thought to act as a cellular signaling inhibitory receptor by recruiting cytoplasmic phosphatases like PTPN6/SHP-1 and PTPN11/SHP-2 via their SH2 domains that block signal transduction through dephosphorylation of signaling molecules. Receptor for PIANP. (Microbial infection) Acts as an entry co-receptor for herpes simplex virus 1.
Synonyms: FDF03
Tractability: Small molecule: a structure with a bound ligand is known. Antibody: UniProt places it where antibodies can reach, with high confidence; its Gene Ontology location is reachable by antibodies, with high confidence; UniProt predicts a signal peptide or a membrane-spanning region. PROTAC: its protein half-life has been measured.
Gene: Protein-coding gene on chromosome 7 (100,367,530 to 100,400,096, forward strand). Ensembl gene ENSG00000085514.
Subcellular location: Cell membrane (Isoform 1); Cell membrane (Isoform 2); Secreted (Isoform 3); Secreted (Isoform 4)
Pathways (Reactome):
Immune System: Immunoregulatory interactions between a Lymphoid and a non-Lymphoid cell
Gene Ontology:
Molecular function: protein binding; MHC class I protein binding
Biological process: signal transduction
Cellular component: extracellular exosome; plasma membrane; extracellular region
Genetic constraint (gnomAD): Loss-of-function variants: 35 observed, 32.57 expected, observed/expected ratio (o/e) 1.07, 90% interval 0.82 to 1.42. The upper end of that interval is the gene's LOEUF score, 1.42, which puts it in group 5 of 6, group 1 being the genes least tolerant of losing a copy. Missense variants: 287 observed, 354.64 expected, observed/expected ratio (o/e) 0.81, 90% interval 0.73 to 0.89. Synonymous variants: 126 observed, 137.74 expected, observed/expected ratio (o/e) 0.91, 90% interval 0.79 to 1.06.
Homologues: Orthologues: chimpanzee PILRA (98% identical), macaque PILRA (78% identical). Paralogues in human: PILRB (62% identical).
Diseases named in the same sentence as PILRA in open-access papers:
PILRA is named in the same sentence as 35 diseases in open-access papers, as found by Europe PMC text mining. Sharing a sentence is not in itself a finding about the gene and the disease. The quoted sentences say what the papers report.
Alzheimer disease (10 papers, 2018 to 2025). A progressive, neurodegenerative disease characterized by loss of function and death of nerve cells in several areas of the brain leading to loss of cognitive function such as memory and language. "All proteins associated with dementia were significant only for vascular or mixed dementia subtypes in secondary analyses, except for PILRA, whose association with dementia appeared to be driven by Alzheimer’s disease." (PMID 41266628, 2025). "Our study unveiled a strong causal association between the PILRA protein and the development of Sick Sinus Syndrome and Alzheimer’s disease." (PMID 38820305, 2024). "The identification of PILRA as a potential risk gene for Alzheimer’s disease underscores the complexity of the genetic landscape contributing to AD." (PMID 39149451, 2024). "PILRA (rs1859788 A > G) has been suggested to be a protective variant for Alzheimer’s disease (AD) and is an entry co-receptor for herpes simplex virus-1." (PMID 35918447, 2022). "We show here that a common missense variant (G78R, rs1859788) of PILRA is the likely causal allele for the confirmed Alzheimer’s disease risk locus at 7q21 (rs1476679)." (PMID 30388101, 2018). "We propose that PILRA G78R protects individuals from Alzheimer’s disease risk via reduced inhibitory signaling in microglia and reduced microglial infection during HSV-1 recurrence." (PMID 30388101, 2018). "Similarly, the PILRA locus was robustly linked via proteomics data (pQTL) to a protective effect in both AD and its proxy phenotype, “Illnesses of mother: Alzheimer’s disease/dementia,” underscoring its consistent role in dementia-related pathways." (PMID 41296471, 2025). "Hence, the PILRA gene variant (G78R, rs1859788) holds the potential as a crucial protective locus against the onset of Alzheimer’s disease." (PMID 38820305, 2024). "Synonymous variant NC_000007.14:g.100373690T>C (rs2405442:T>C) in the Paired Immunoglobulin-like Type 2 Receptor Alpha (PILRA) gene was previously associated with decreased risk for Alzheimer’s disease (AD) in genome-wide association studies, but its biological impact is largely unknown." (PMID 39829933, 2025). "For instance, the PILRA protein presents a pleiotropic effect on sick sinus syndrome and Alzheimer’s disease, whereas GRN exerts specific effects on the latter." (PMID 38820305, 2024). "Our study corroborates prior research, underscoring the PILRA protein’s efficacy as a robust therapeutic target for Alzheimer’s disease." (PMID 38820305, 2024). "Specifically, the PILRA protein presents a pleiotropic effect on both sick sinus syndrome and Alzheimer’s disease, whereas GRN exerts specific effects on the latter." (PMID 38820305, 2024). "The present study has identified PILRA protein as a pleiotropic protein target in sick sinus syndrome and Alzheimer’s disease." (PMID 38820305, 2024). "Thus, identifying PILRA as a promising therapeutic target for sick sinus syndrome and Alzheimer’s disease carries significant clinical implications." (PMID 38820305, 2024).
dementia (3 papers, 2025 to 2026). Loss of intellectual abilities interfering with an individual's social and occupational functions. "Overall, 30 cSVD-associated proteins (61%) were associated at P < 0.05 and 18 at PFDR < 0.05 with stroke or dementia (both for PILRA and PRSS8)." (PMID 41266628, 2025). "Using delirium in the dementia-free UKB GWAS as outcome, ADAM8, CCL25, PILRA and LAYN lost their MR causal effect significance (FDR q > 0.05)." (PMID 41286463, 2026).
breast carcinoma (2 papers, 2025 to 2026). "This study investigated the expression, mutation, and DNA methylation patterns of PILRA in breast cancer, along with its impact on immune infiltration and associated pathways." (PMID 41624853, 2026). "PILRA, MKI67, and UBE2C, as potential diagnostic and prognostic biomarkers, are anticipated to serve as promising therapeutic targets for the clinical management of both breast cancer and thyroid cancer." (PMID 41328437, 2025).
diabetes (2 papers, 2024). "APOE and PILRA have been previously linked to diabetes, a condition that may be comorbid with allergic diseases." (PMID 38773393, 2024). "Interestingly, PILRA has also been found to be decreased in skeletal muscle of patients with obesity and T2D, and thrombospondin 1 has been linked to β-cell lipotoxicity and diabetic retinopathy, suggesting an important role of these sex-specific changes in diabetes pathogenesis." (PMID 38032738, 2024).
age-related macular degeneration (1 paper, 2018). Age-related loss of vision in the central portion of the retina (macula), secondary to retinal degeneration. "Of interest, the G allele of rs6955367 (increased expression of PILRB) is linked to rs7803454 (r2 = 0.83), a variant associated with increased risk of age-related macular degeneration and suggests the presence of independent effects in the PILRA/PILRB region." (PMID 30388101, 2018).
anemia (1 paper, 2024). A reduction in the number of red blood cells, the amount of hemoglobin, and/or the volume of packed red blood cells. "A phewas indicated that PILRA SNP rs1859788 is associated with megaloblastic anemia, which may explain an observed association between AD and anemia." (PMID 39149451, 2024).
glaucoma (1 paper, 2024). Increased pressure in the eyeball due to obstruction of the outflow of aqueous humor. "A total of 11 unique protein-coding genes posterior probability (PP) of H4 > 0.70 finally remained, including GSTM3 for senile cataract, WARS1, C3, IGFBP7, and PILRA for AMD, ECI1, LCT, and NPTXR for glaucoma, EFEMP1 for myopia, and SIRPG and SIGLEC14 for DR." (PMID 39408566, 2024).
glioma (1 paper, 2021). A benign or malignant brain and spinal cord tumor that arises from glial cells (astrocytes, oligodendrocytes, ependymal cells). "Multivariate Cox analysis revealed that genes such as PILRA, LILRB2, and BATF were independent prognostic factors for glioma patients." (PMID 34540893, 2021).
Intellectual disability (1 paper, 2020). "Homozygous mutations in AP4M1, located in the region including PILRA and STAG3, cause spastic tetraplegia, intellectual disability, and white matter loss." (PMID 30108311, 2020).
liver cancer (1 paper, 2021). An epithelial or non-epithelial malignant neoplasm that arises from the liver. "Interaction with PILRA intracellular domain to activate downstream JAK/STAT signaling pathway to induce apoptosis of liver cancer cells." (PMID 34888249, 2021).
sick sinus syndrome (1 paper, 2024). A constellation of signs and symptoms which may include syncope, fatigue, dizziness, and alternating periods of bradycardia and atrial tachycardia, which is caused by sinoatrial node dysfunction. "In this study, we report for the first time that PILRA protein may also serve as a therapeutic target for sick sinus syndrome and provide highly recommended level evidence." (PMID 38820305, 2024).
thyroid cancer (1 paper, 2025). "In summary, this study suggests that PILRA, MKI67, and UBE2C may serve as both diagnostic biomarkers and therapeutic targets for breast and thyroid cancers." (PMID 41328437, 2025).
tumor (11 papers, 2021 to 2026). "PILRA was involved in immune infiltration and modulated the abundance of various immune cells and the tumor microenvironment, suggesting a role in immune regulation and tissue maintenance." (PMID 41624853, 2026). "Further study is needed to verify the clinical value of PSTPIP1 and PILRA in the additional samples and to explore their molecular functions in tumor immune regulation." (PMID 35571056, 2022). "Given that LUAD differentiation can influence the expression of PD-L1, we further explored the correlation between PSTPIP1/PILRA and tumor differentiation." (PMID 35571056, 2022). "We found CAFs which highly expressed CTHRC1 (from F04 and F08) and tumor associated macrophages were mediated by a different set of ligand-receptor pairs, including THY1/aXb2 complex, GRN/TNFRSF1A, CD99/PILRA, CD74/MIF, APP/CD74, ANXA1/FPR1, etc." (PMID 35928443, 2022). "In this study, elevated PILRA expression in both BC and TC coincided with increased monocyte infiltration, supporting the hypothesis that PILRA may mediate tumor progression through immune regulation." (PMID 41328437, 2025). "Moreover, compared with ductal-normal and ductal-tumor cells, CD55_ADGRE5, CD99_PILRA, ANXA1_FPR3 interactions were drastically upregulated in the malignant cells." (PMID 35087839, 2021). "This revealed several strong putative interactions between GBM tumor cell ligands and macrophage receptors that were conserved over the different co‐cultures, including APP:CD74, CD99:PILRA, PTN:ALK, and CLU:TREM2." (PMID 37791581, 2023). "Compared to PD-L1–negative LUAD tissues, the protein levels of PSTPIP1 and PILRA were relatively increased in the PD-L1–positive tissues, and the expression of PSTPIP1 and PILRA positively correlated with the tumor-infiltrating lymphocytes." (PMID 35571056, 2022). "Many signals favoring tumor cells were significantly activated in C2, such as integrin-related signals (COL9A3 − (ITGA2+ITGB1), JAM3 − (ITGAM+ITGB2), COL6A1 − (ITGA1+ITGB1)), immune suppression signals (CD99 − PILRA), etc.." (PMID 39391717, 2024). "Besides, PILRA expression was positively correlated with ESTIMATE scores and the abundances of tumor-infiltrating immune cells." (PMID 37652967, 2023). "Therefore, to some extent, we can exclude the possibility that PSTPIP1 and PILRA levels are correlated with tumor differentiation rather than immune biomarkers." (PMID 35571056, 2022). "Except for PSTPIP1 and PILRA, the other genes with high scores have been identified to have functionally relevant roles in the immune checkpoint, tumoral immune cells, and immune infiltration, while few studies have reported the role of PSTPIP1 and PILRA in tumor immunity." (PMID 35571056, 2022).
cancer (3 papers, 2023 to 2025). A tumor composed of atypical neoplastic, often pleomorphic cells that invade other tissues. "According to Kaplan–Meier plotter website, PILRA expression was positively associated with prognosis of cancer patients receiving immunotherapy, including anti-PD1, anti-PD-L1 and anti-CTLA-4." (PMID 37652967, 2023). "Concurrently, PILRA expression was significantly associated with predictive biomarkers of cancer immunotherapy, and positively correlated with the prognostic outcomes of cancer patients receiving immunotherapy." (PMID 37652967, 2023). "PILRA was significantly dysregulated and frequently mutated in pan-cancer." (PMID 37652967, 2023). "High expression of PILRA enhances the effect of antitumor immunotherapy, but its effects vary in different cancers.On the other hand, MYOIF, ILRA2, and NCF1 are considered prognostically unfavorable factors." (PMID 38799454, 2024). "This study uncovered the immunological roles of PILRA in cancers and its potential as a novel biomarker and therapeutic target for cancer immunotherapy." (PMID 37652967, 2023). "In the current study, we comprehensively analyzed the oncogenic and immunologic roles of PILRA at a pan-cancer level based on the Cancer Genome Atlas and Gene Expression Omnibus datasets." (PMID 37652967, 2023). "Therefore, our study provided novel bioinformatics evidence supporting the potential involvement of PILRA in cancer immunity in various cancers." (PMID 37652967, 2023). "Our study offers a comprehensive insight into the prognostic and immunological roles of PILRA across various cancers, and might facilitate the discovery of novel biomarkers and genetic drivers regarding cancer immunity." (PMID 37652967, 2023). "However, the roles of PILRA in cancer immunity remain unexplored yet." (PMID 37652967, 2023). "Among these, PILRA, MKI67, and UBE2C showed consistently elevated expression in both cancers and were validated through RT-qPCR and immunohistochemistry, suggesting their potential as therapeutic targets." (PMID 41328437, 2025). "Subsequently, we selected PILRA, MKI67, and UBE2C, which were significantly upregulated in both cancer types, for further validation using immunohistochemistry." (PMID 41328437, 2025). "In BC tissues, TAP1, PILRA, UBE2C, TMEM51, and MKI67 were significantly upregulated, while the expression levels of SPP1 and CENPF remained unchanged between cancer and adjacent tissues." (PMID 41328437, 2025).
neurodegenerative disease (2 papers, 2025). A disorder of the central nervous system characterized by gradual and progressive loss of neural tissue and neurologic function. "Paired immunoglobin like type 2 receptor alpha (PILRA) has long been recognized as a risk gene for AD; alongside other functional genes that participate in neuroinflammation are putative or proven calmodulin-binding proteins for other neurodegenerative diseases." (PMID 39975850, 2025).
PILRA also shares sentences with these, for which no sentence is quoted: infection (3 papers); frontotemporal dementia (2); Parkinson disease (2); Stroke (2); viral infection (2); allergic disease (1); cerebral amyloid angiopathy (1); cognitive defects (1); COVID-19 (1); delirium (1); diabetic retinopathy (1); glioblastoma (1); Huntington disease (1); ischemic stroke (1); myopia (1); Obesity (1); pancreatic cancer (1); prostate carcinoma (1); Sepsis (1); Spastic tetraplegia (1).